ENSG00000257411 (novel protein)
Gene: Protein-coding gene on chromosome 12 (56,101,331 to 56,109,289, forward strand). Ensembl gene ENSG00000257411.
Genetic constraint (gnomAD): Loss-of-function variants: 1 observed, 12.42 expected, observed/expected ratio (o/e) 0.0805, 90% interval 0.028 to 0.38. Missense variants: 55 observed, 159.63 expected, observed/expected ratio (o/e) 0.34, 90% interval 0.28 to 0.43. Synonymous variants: 48 observed, 53.4 expected, observed/expected ratio (o/e) 0.9, 90% interval 0.71 to 1.14.